ENG (endoglin)
Diseases named in the same sentence as ENG in open-access papers (continued):
Sharing a sentence is not in itself a finding about the gene and the disease.
tumor (continued). "Second, analyses performed on tumor lysates revealed that chemokines involved in myeloid cell migration (CCL5, CCL2, CCL4), together with inflammatory (IL-1β and TNFα) and pro-angiogenic factors (VEGF-A, VEGFR2, PDGF, Endoglin) were increased in tumors of mice fed a HFHCD." (PMID 36104342, 2022). "Also, TGFB1, ENG, B2M, HLA-F, SELPLG, and ITGB2 were significantly increased in tumor-associated macrophages, compared with those nontumor-associated macrophages." (PMID 36249427, 2022). "It has been reported that MMP-14 could inhibit tumor angiogenesis by mediating the shedding of endoglin, thereby exerting a negative effect on tumor progression." (PMID 31956360, 2020). "All these observations have led to the assumption that the worse prognosis of tumors with high levels of endoglin is due to greater angiogenesis and, therefore, greater tumor growth, although this hypothesis has not been experimentally demonstrated." (PMID 31897911, 2020). "Furthermore, in carcinoma, these effects were less evident, and a moderate increase of immune cell infiltration and no tumor cures were observed, as seen in the study silencing endoglin with GET." (PMID 32204304, 2020). "Another mechanism of endothelial anergy includes the secretion of soluble adhesion molecules by tumor cells (MCAM/sCD146 and Endoglin) that indirectly inhibit TIL recruitment by competing with EC bound-receptors and by direct VEGF-synergistic interactions with tumor angiogenesis." (PMID 32974337, 2020). "BMP9-endoglin signaling induces YAP/SMAD nuclear translocation driving the expression of inflammatory genes in ECs, implying that endothelial YAP-SMAD may regulate tumor angiogenesis." (PMID 33614496, 2020). "Endoglin (CD105) is a cell membrane glycoprotein overexpressed on proliferating endothelial cells that binds several factors of the TGF-β superfamily, suggesting that activation of this pathway may be responsible for tumor VEGF-independency." (PMID 31817884, 2019). "Currently, neither endoglin nor CD34 expression adequately reflects true MVD values in tumor tissues, and the use of Abs to both antigens may be necessary to achieve realistic results." (PMID 29748768, 2018). "The exact role of endoglin in angiogenesis remains unclear, although it has been demonstrated that the presence of endoglin in the tumor vascular endothelium is a negative predictive factor in various types of solid tumors." (PMID 29748768, 2018). "Higher endoglin expression in non-tumour area, as compared with tumour tissue, suggests that this location may play a very important role in the progression of HCC." (PMID 30563158, 2018). "The local regulation of endoglin shedding, mediated by regulation of endothelial MMP-14 expression, could result in remarkable changes in soluble endoglin concentration in the tumour microenviroment, with consequent effects on the angiogenic potential of tumour-associated endothelial cells." (PMID 26296972, 2015). "The reason for these results in our study could be in the fast growing TS/A tumors that do not express endoglin, therefore the therapy was affecting only tumor endothelial cells." (PMID 25909447, 2015). "However, the effect of silencing of endoglin on in vitro antiangiogenic potential and in vivo tumor growth reduction has not been studied yet." (PMID 23593103, 2013). "After a single electrotransfer of m_siRNA 869 in TS/A tumors in vivo, no statistically significant reduction of tumor growth was observed even though endoglin mRNA level was statistically significantly reduced for ∼50% in comparison to the untreated control tumors at day 2 after the treatment." (PMID 23593103, 2013). "Interestingly, only individual SCC cells in the tumor express endoglin, while the majority do not." (PMID 37396898, 2023).
tumor (continued). "Thus, a Bi-FAP/mEnd-IL formulation tailored for the targeting of human endoglin and FAP will be suitable for the targeted delivery of drugs and contrast agents into human neoplastic cells, and the tumor microenvironment components including the TAFs, tumor vasculature and also TAMs." (PMID 32316521, 2020). "Importantly, both endoglin and ALK1 are emerging as successful targets for cancer therapies in the general population: The use of a soluble chimeric protein (ALK1-Fc), an inhibitor of ALK-1, has been shown to result in significant tumour-suppression both in vitro and in vivo." (PMID 24354965, 2013). "IHC analysis demonstrated that ENG was highly expressed in SUM102-MerTK metastatic tumor cells in the lung, whereas metastatic SUM102-V did not express ENG." (PMID 38791148, 2024). "Although knocking out ENG in SUM102-MerTK clone did not affect cell migration and cell proliferation/tumor growth, it did significantly reduce lung metastasis." (PMID 38791148, 2024). "Although the authors were able to image angiogenesis by using a planar NIRF imager and endoglin- and VEGFR2-specific contrast agents, an important limitation was the lack of additional cell types serving as a tumor environment." (PMID 33946583, 2021). "Thus, contrary to what had been hypothesized, endoglin overexpression does not result in an increase in tumor growth or tumor vascularization but results in even poorer quality tumor vessels, facilitating the intravasation and metastasis of tumor cells." (PMID 31897911, 2020). "CD105/endoglin is not essential for tumor initiation in this study, but marks a rare, highly tumorigenic subpopulation of RCC tumor-initiating cells in some cell lines." (PMID 28404888, 2017). "Other tumours markers studied for diagnosis of BOT, as CA 19.9, Tissue polypeptide antigen, Carcinoembryonic antigen, Endoglin and Tetranectin have not demonstrated be useful." (PMID 25729420, 2015). "Endoglin protein expression was also observed in a dose-dependent pattern only in the HUVECs, not in CT26 or LL/2 tumor cells (left)." (PMID 23209720, 2012). "In vivo experiments indicated endoglin protein in the CT26 and LL/2 tumor tissues treated with toxicarioside A but not in the tumor tissues treated with DMSO (right)." (PMID 23209720, 2012). "We found that targeting to VEGFR2, endoglin, or the VEGF:VEGFR complex was specific for tumor vasculature as there was no signal enhancement in nontumor tumor tissue." (PMID 20628530, 2010). "IHC analysis revealed strong ENG expression in the membrane and cytoplasm of tumor cells in the lungs of mice injected with SUM102-MerTK clones, whereas no ENG expression was observed in tumor cells in the lungs of mice injected with SUM102-V." (PMID 38791148, 2024). "It appears clear that T98G, although originating from GBM, behave quite differently as their capacity to generate tumor-spheres was null in our hands, and neither PROM1 nor ENG expression were induced under hypoxia conditions, as occurred with the rest of GBM cells." (PMID 33396280, 2020). "In the TCGA_LIHC cohort, 16 of 120 genes were downregulated in HCC tissue rather than in adjacent non-tumor tissue, and 9 of 16 genes, namely, ALDH8A1, C11orf96, CLYBL, EFNB3, ENG, NPC1L1, PIM3, SEC14L2, and SLC8A1, displayed a significant difference (p < 0.05)." (PMID 33352935, 2020). "To obtain further insight into tumor vascularization and VEGFR expression by cancer and non-tumor cells, we used real-time qRT-PCR to quantify species-specific mRNAs of PECAM1/CD31, ENG/CD105, FLT1/VEGFR1, KDR/VEGFR2 and VEGFA genes in a large series of 150 xenografts from different tumor types." (PMID 24625025, 2014).
cancer (233 papers, 2003 to 2026). A tumor composed of atypical neoplastic, often pleomorphic cells that invade other tissues. "While MCAM, VE-cadherin, and Endoglin contribute to angiogenesis, and angiogenesis can be therapeutic in the context of repair after injury, VE-cadherin- and Endoglin-associated angiogenesis is more often implicated in cancer angiogenesis." (PMID 39518030, 2024). "These mutations are located across the entire ENG gene in cancer, including in the Zona pellucida-like domains." (PMID 39247590, 2024). "Targeting endoglin in cancer-associated fibroblasts by TRC105 inhibited fibroblast invasion in vitro." (PMID 36614087, 2022). "Plasma endoglin level was also independently associated with cancer‐specific and overall survival in both pre‐ and postoperative models (all p < 0.05), as well as with recurrence‐free survival (RFS) in the preoperative model (p < 0.001)." (PMID 34587660, 2022). "Inhibins have been widely used as a diagnostic marker for a subset of cancers and both betaglycan and endoglin have been evaluated as therapeutic strategies in cancer." (PMID 33819300, 2021). "An important role in angiogenesis is linked to endoglin, which is required for neo-angiogenesis in tumors, and to the metastatic potential of cancer cells, which is affected by TGFβ receptor signaling modulation." (PMID 34579743, 2021). "Endothelial cells in the newly synthesized blood vessels in the TME significantly express the TGF-β co-receptor endoglin, which has been linked with poor prognosis and metastatic disease in many cancer cells, including TNBC." (PMID 35010954, 2021). "In this review, we will provide a summary of recent publications on endoglin expression on epithelial (cancer) cells, cancer-associated fibroblasts, and mesenchymal stem cells." (PMID 32059544, 2020). "Whereas it has been demonstrated that the deficiency of endoglin leads to minor and defective angiogenesis, little is known about the effect of its increased expression, characteristic of several types of cancer." (PMID 31897911, 2020). "For example, beyond its antiangiogenic effect on the endothelium, anti-endoglin treatment inhibits cancer-associated fibroblast (CAF) invasion and metastasis." (PMID 31897911, 2020). "This meta-analysis reviews and evaluates the association between ENG expression and prognosis in cancer patients." (PMID 29484142, 2018). "Endoglin expression has revealed its prognostic and diagnostic value in other circumstances, being a potential vascular target for antiangiogenic cancer therapy." (PMID 21171985, 2010). "Abnormal functions of endoglin are important for various cellular processes implicated in cancer." (PMID 35409247, 2022). "Next to its key role in regulating angiogenesis, endoglin is expressed by neoplastic epithelial cells, hematopoietic stem cells, innate immune cells, adaptive immune cells, (cancer-associated) fibroblasts, and mesenchymal stem cells, as reviewed by Schoonderwoerd and colleagues." (PMID 33946583, 2021). "However, more recent studies have reported novel roles for endoglin signaling in (cancer-associated) fibroblasts (CAFs), Mesenchymal Stromal Cells (MSCs), epithelial cancer cells, and various immune cell subpopulations." (PMID 32059544, 2020). "It has been suggested that endoglin deficiency results in angiogenic adaptation, weakens the endothelial barrier, and increased metastatic spread and may be associated with cancer progression." (PMID 27102733, 2016). "It has been suggested that endoglin deficiency results in angiogenic adaptation, weakens the endothelial barrier, and increases metastatic spread, and may be associated with cancer progression." (PMID 26089870, 2015). "Furthermore, endoglin suppresses cancer metastasis, which is associated with decreased expression in several Smad1-responsive genes." (PMID 22929622, 2012).
cancer (continued). "Although endoglin upregulation in CAFs could be considered controversial as high levels of this TGFβ1 co-receptor have been associated to more aggressive cancer variants 35, here we provide evidence for the first time that the response of cSCC to PDT can be improved by using this strategy." (PMID 40384860, 2025). "Since filopodia have been implicated in both of these behaviors, we tested the role of endoglin in promoting cancer metastasis in this model." (PMID 41532547, 2026). "Proteomic analyses of cancer cell-derived SEVs identified the TGF-β family coreceptor endoglin as a key SEV-enriched cargo that regulates filopodia." (PMID 41532547, 2026). "Endoglin was found to promote filopodia formation by cancer cells, as well as the filopodia-dependent behaviors of cancer cell metastasis and 3D motility." (PMID 41532547, 2026). "Altogether, we identify THSD7A carried by exosomes as a key controller of filopodia formation in diverse cell types and further identify endoglin as a key regulator of THSD7A secretion in exosomes in cancer cells." (PMID 41532547, 2026). "We discovered a single SEV cargo that was altered in endoglin-KD cancer SEVs, the transmembrane protein Thrombospondin Type 1 Domain Containing 7A (THSD7A)." (PMID 41532547, 2026). "Cancer cell endoglin levels also affected filopodia-dependent behaviors, including metastasis of cancer cells in chick embryos and 3D migration in collagen gels." (PMID 41532547, 2026). "By contrast, CAMs from chick embryos injected with endoglin-KD HT1080 cells had reduced numbers of individual metastatic cancer cells and colonies." (PMID 41532547, 2026). "To validate our finding that THSD7A levels are downregulated in SEVs from endoglin-KD cancer cells, we performed Western blot analysis of control and endoglin-KD SEVs from B16F1 and HT1080 cells." (PMID 41532547, 2026). "When compared with corresponding healthy tissues from 33 types of cancer tissues, ENG expression is decreased in most cancer types (13 types) and increased in some cancer types (5 types)." (PMID 39247590, 2024). "Despite the fact that the role of endoglin on endothelial cells has been extensively described, its expression and biological role on (epithelial) cancer cells is still debatable." (PMID 37396898, 2023). "Endoglin, also known as CD105, is an endothelial cell membrane glycoprotein that is highly expressed in the neovascularization of cancer cells including HCC, which was first discovered in 1990s and initially named as the 44G4 antigen." (PMID 35624643, 2022). "ENG is a MSC marker reported to be highly expressed by active endothelial cells during angiogenesis as well as in an extensive number of cancers and is associated with poor prognosis." (PMID 35955799, 2022). "In cancer therapy, multiple research antibodies against endoglin have been developed, including TRC105." (PMID 36614087, 2022). "Rationale: Endoglin, also known as CD105, is a homo-dimeric membrane glycoprotein required for angiogenesis and serves as a marker for cancer vasculature." (PMID 33995664, 2021). "This review will give a systematic overview of the use of endoglin as a molecular target for imaging of cancer and cardiovascular diseases, including (pre) clinical applications such as IGS and diagnostics." (PMID 33946583, 2021). "Cancer stem-like cells isolated from Hepatitis C (HCV)-infected primary hepatocytes and transformed human hepatocytes were compared, showing endoglin upregulation of up to 250-fold in sphere-forming cells (cancer stem cells)." (PMID 33809908, 2021). "The PubMed search on endoglin-based imaging for cancer and cardiovascular diseases revealed a total of 476 articles." (PMID 33946583, 2021). "For stroma, the marker genes used were VWF, ENG, and CDH5 (for endothelial cells), DCN, ACTA2, and FAP (for cancer-associated fibroblasts), and PTPRC, CD4, and CD163 (for leukocytes)." (PMID 33810510, 2021).
cancer (continued). "Based on predominantly preclinical data, endoglin-based imaging shows promising results in both cancer and cardiovascular diseases." (PMID 33946583, 2021). "Used as a marker for activated endothelial cells, endoglin has proven itself as a potent prognostic indicator for cancer patients, predicting poor outcomes for overall, disease free, and cancer-specific survival." (PMID 33946583, 2021). "Our and prior mechanistic studies in cancer indicate a strong dependency of inhibin function on betaglycan and endoglin." (PMID 33819300, 2021). "Although, betaglycan and endoglin are not only structurally related but also of the highest importance for cancer development and progression." (PMID 34501347, 2021). "ENG mainly regulates malignant phenotypes of cancer cells by modulating TGFβ/BMP signaling, yet it also acts through other SMAD-independent mechanisms." (PMID 33804796, 2021). "In cancer, betaglycan and endoglin impact disease progression by regulating cell migration, invasion, proliferation, differentiation, and angiogenesis in multiple cancer models." (PMID 33819300, 2021). "We examined BiTE binding to endoglin-expressing cells and its effects on the cytolytic activity of T cells and cancer development." (PMID 33995664, 2021). "Clustering analysis for genes correlated with INHA, TGFBR3, or ENG in cancers revealed ENG and TGFBR3 had very few genes correlated exclusively to one or the other." (PMID 33819300, 2021). "ENG is expressed strongly in proliferating ECs but also in cancer cells from different types of tumors." (PMID 33804796, 2021). "Prior and emerging studies reveal the dichotomous functions of inhibin’s on cancer depending on either betaglycan or endoglin." (PMID 33819300, 2021). "Samples from both cancer types were analyzed for the expression of two putative biomarkers, Endoglin and VEGF." (PMID 32434528, 2020). "Most of the studies concerning Endoglin and cancer have focused on its role as a proangiogenic factor and its utility as an MVD (micro-vessel density) marker." (PMID 32434528, 2020). "Soluble endoglin can inhibit angiogenesis and its levels have been shown to be upregulated in pre-eclampsia, metabolic disorders and in cancer, although for the latter, conflicting reports have been published." (PMID 33375670, 2020). "Endoglin is a 180-kDa glycoprotein receptor primarily expressed by the vascular endothelium and involved in cardiovascular disease and cancer." (PMID 31540324, 2019). "Increase in endoglin production is observed mostly in proliferating ECs of small vascular and lymphatic vessels in cancer tissues, including HCC." (PMID 30563158, 2018). "Considering the fact that HCC is one of the most vascularised solid tumours, evaluation of angiogenesis with the use of anti-endoglin mAb should be included in the routine diagnostics and prognostic procedures in this type of cancer." (PMID 30563158, 2018). "In previous report we showed an effective induction of cytotoxicity of cytotoxic T-lymphocytes directed against endothelial and cancer cells overexpressing endoglin." (PMID 29320562, 2018). "Apart from the ECs, a range of other cells involved in angiogenesis in this type of cancer, which is also characterised by positive endoglin expression, was described." (PMID 30563158, 2018). "This form of endoglin is released into the bloodstream not only by ECs, but also by cancer cells that contain endoglin on their surface." (PMID 30563158, 2018). "A phase I study using an anti-endoglin monoclonal antibody (TRC105) in combination with bevacizumab in adults with advanced cancers showed good tolerance and clinical activity in a VEGF inhibitor-refractory population." (PMID 29304781, 2018). "The gene expression levels of SPARCL1 and TAL1 were down-regulated in all the eight cancer tissues compared with their paired adjacent normal tissues, while ENG was down-regulated in six of the eight cancer tissues." (PMID 28178989, 2017).